TIMP1 (TIMP metallopeptidase inhibitor 1)
Diseases named in the same sentence as TIMP1 in open-access papers (continued):
Sharing a sentence is not in itself a finding about the gene and the disease.
breast carcinoma (continued). "We validated and applied two different MMP-9:TIMP-1 assays and found that both the commercially available ELISA and the PLA reliably quantified the MMP-9:TIMP-1 complex concentration in plasma samples from breast cancer patients." (PMID 24330623, 2013). "Linear regression slopes of their dose–response curves were close to zero for breast cancer, colon cancer, hepatocellular carcinoma, and lung cancer, indicating that serum TIMP-1 had little or no UEA fucosylation in these cancer conditions." (PMID 24015777, 2013). "Further, there was no relation between MMP-9:TIMP-1 and outcome when combining the parameters in a multivariate analysis, suggesting that the MMP-9:TIMP-1 complex has no value as a stand-alone prognostic marker in breast cancer." (PMID 24330623, 2013). "Combined analysis of both serum TIMP-1 and HER2 ECD may have additional value when used for the clinical management of breast cancer patients with HER2 overexpression in Taiwan." (PMID 22339939, 2012). "We examined the effect of NO on TIMP-1 mRNA and protein levels in MDA-MB-231 breast cancer cells." (PMID 22957045, 2012). "Together, these results suggest that the effects of aberrantly high TIMP-1 and NOS2 on breast cancer outcome may be mechanistically interrelated." (PMID 22957045, 2012). "For example, TIMP-1 inhibits HSC apoptosis via MMP inhibition, while the anti-apopotic effect of TIMP-1 on human breast carcinoma cells does not require MMP inhibition." (PMID 21711826, 2011). "Breast tumor cells and ES cells secrete cytokines and chemokines to their microenvironment, however, breast cancer cells secrete a significantly higher level of soluble factors, which is correlated with tumor metastasis (e.g., M-CSF, OSM, MIP-2/CXCL-2, MMP-9, TIMP-1)." (PMID 22174624, 2011). "A negative prognostic impact of serum TIMP-1 as well as tissue protein levels was described in breast cancer, colorectal cancer, and other malignancies." (PMID 21745383, 2011). "We then analyzed TIMP-1, TIMP-3 and RECK mRNA expression and focused on the expression of different MMP proteins in stromal fibroblasts to identify a possible role in canine mammary tumors." (PMID 21726449, 2011). "Study using breast cancer samples demonstrates that the expressions of MMP-1, MMP-2, MMP-3, MMP-9, urokinase-type PA, and tissue-type PA, and inhibitors (TIMP-1 and TIMP-2) were stronger or equivalent in tumor cells than in fibroblasts or inflammatory cells within the tumor section." (PMID 21152266, 2010). "In two breast cancer studies lack of tumour cell TIMP-1 immunoreactivity or low levels of TIMP-1 in tumour homogenates predicted sensitivity to antracycline-containing therapy but not to cyclophosphamide, methotrexate and 5-fluorouracil in adjuvant treatment." (PMID 20459644, 2010). "A negative prognostic impact of serum TIMP-1 has also been observed in breast cancer, colorectal cancer and other malignancies." (PMID 20388222, 2010). "Here, we propose a more comprehensive approach by analyzing the expression levels of several MMPs (MMP-2, MMP-9 and MMP-14) and MMP inhibitors (TIMP-1, TIMP-2 and RECK) in different models (five human breast cancer cell lines, 72 primary breast tumors and 30 adjacent normal tissues)." (PMID 19144199, 2009). "We analyzed the expression levels of MMP-2, MMP-9 and MMP-14 and their inhibitors (TIMP-1, TIMP-2 and RECK) by quantitative RT-PCR (qRT-PCR) in five human breast cancer cell lines presenting increased invasiveness and metastatic potential, 72 primary breast tumors and 30 adjacent normal tissues." (PMID 19144199, 2009). "Here, we proposed a more extensive approach by analyzing the mRNA expression levels of different MMPs (MMP-2, MMP-9 and MMP-14) and MMP inhibitors by qRT-PCR (TIMP-1, TIMP-2 and RECK) in several models (five human breast cancer cell lines, 72 primary breast tumors and 30 adjacent normal tissues)." (PMID 19144199, 2009).
breast carcinoma (continued). "Moreover, all analyzed MMPs inhibitor (TIMP-1, TIMP-2 and RECK) are also over-expressed in MDA-MB-435, MDA-MB-231 and Hs578T breast cancer cells." (PMID 19144199, 2009). "However, elevated mRNA expression levels of TIMP-1 and TIMP-2 have been previously detected in breast cancer cell lines with high invasive and metastatic potential." (PMID 19144199, 2009). "Accordingly, it has been reported that several other MMPs and TIMPs may be overexpressed and/or related to clinical outcome in breast cancer, such as MMP-11 MT1-MMP (MMP-14) MMP-13, TIMP-1 or TIMP-2." (PMID 17848954, 2007). "Recent studies suggest that TIMP-1 has prognostic value in head and neck SCC, colorectal carcinoma, ovarian carcinoma and breast carcinoma." (PMID 19662197, 2007). "Levels of MMP-8 and -9 correlated significantly with each other and with TIMP-1 levels, but were not related to tumour size or prognosis in human breast cancer." (PMID 16940985, 2006). "Additionally, two breast cancer cell lines, MCF-7 and BC-61, have been shown to respond to TIMP-1 by an increase in proliferation." (PMID 14735194, 2004). "In the liver, high levels of tissue inhibitor of metalloproteinases 1 (TIMP-1) secreted by hepatocytes upregulate stromal cell-derived factor 1 (SDF-1), fibronectin, TGF-β, urokinase-type plasminogen activator (uPA), and S100A, inducing homing of breast cancer cells to this distant microenvironment." (PMID 37440925, 2023). "We have previously found that tumors derived from MDA-MB-231 human breast cancer cells orthotopically implanted in mice show evidence of gelatinase activity, and that treatment of MDA-MB-231 cells with tissue inhibitor of metalloproteinases-1 (TIMP-1) can reduce cellular invasiveness." (PMID 24811362, 2014). "Measurement of the MMP-9:TIMP-1 protein:protein complex concentrations in plasma from breast cancer patients for prognostic purposes has not previously been described although numerous publications have indicated that both molecules, when measured individually, are indicative of patient prognosis." (PMID 24330623, 2013). "This study could not confirm the predictive value of TIMP-1 immunoreactivity in patients randomized to receive E-CMF versus CMF as adjuvant treatment for primary breast cancer." (PMID 23570501, 2013). "Indeed, TIMP-1 suppression enhanced chemotherapeutic sensitivity and tumor cell apoptosis by inhibiting Akt signaling, while its overexpression promoted tumor aggressiveness of MDA-MB-231 breast cancer cells." (PMID 22957045, 2012). "We recently extended the in vitro studies to a human breast carcinoma cell line and showed that cells expressing high levels of TIMP-1 protein were significantly less sensitive to treatment with etoposide and epirubicin than cells expressing low levels of TIMP-1." (PMID 19744322, 2009). "Despite earlier reports linking MMP-9 and TIMP-1 with prognosis in breast cancer patients, we here demonstrate that plasma levels of the MMP-9:TIMP-1 protein complex hold no prognostic information in primary breast cancer as a stand-alone marker." (PMID 24330623, 2013). "In conclusion, it is unclear whether HIIT influences levels of MMP in breast cancer patients undergoing anthracycline-based chemotherapy yet MMP-2 was significantly increased both the HIIT and CON group; with no changes on MMP-1, -7, -10, TIMP-1 and -2." (PMID 32246106, 2020). "Furthermore, these data also demonstrate that 1–4 freeze/thaw cycles, which corresponds to the number of cycles for the analysed breast cancer samples, do not affect the levels of MMP-9:TIMP-1 complex, thereby eliminating the concern of complex degradation upon repeated freeze/thaw cycles." (PMID 24330623, 2013).
colorectal cancer (96 papers, 1999 to 2026). A primary or metastatic malignant neoplasm that affects the colon or rectum. "Prospective cohort studies indicate that higher levels of TIMP1 in patients with GC and colorectal cancer are associated with poorer prognosis." (PMID 40535808, 2025). "Reduced TIMP1 levels have been linked to heightened tumour aggressiveness and poor survival among colorectal cancer patients." (PMID 39120548, 2024). "Further analysis revealed TIMP1 as the most valuable diagnostic and prognostic biomarker for colorectal cancer, with IHC experiments verifying its high expression." (PMID 37842645, 2023). "There have been some promising results regarding the diagnostic value of TIMP-1 for patients with colorectal cancer (CRC)." (PMID 30458003, 2018). "In line with our report, high TIMP-1 protein expression levels in tumor tissue or in plasma obtained pre-operatively have been associated with poor prognosis in breast and colorectal cancer amongst others." (PMID 27619981, 2016). "TIMP1 levels are increased in cancer patients, particularly in those with breast or colorectal carcinoma, and this augment is negatively associated with patient outcome." (PMID 23522389, 2013). "More recently, TIMP-1 levels have been associated with response to therapy of breast and colorectal cancer." (PMID 20459644, 2010). "TIMP1 encodes for a peptidase involved in the degradation of the extracellular matrix and has been shown to be upregulated in breast and gastric cancer, whilst also being highlighted as a potential biomarker for colorectal cancer." (PMID 40998421, 2025). "Studies have demonstrated that TIMP1 may be involved in promotion of progression of colorectal cancer, possibly serving as a prognostic hallmark for colorectal cancer." (PMID 32420905, 2020). "In another study in which colorectal cancer patients were treated with irinotecan, 5-fluorouracil and folinic acid, low plasma TIMP-1 was significantly and independently associated with higher probability of obtaining an objective response to chemotherapy (OR = 3.5, p = 0.007)." (PMID 20459644, 2010). "TIMP-1 expression has also been reported to be associated with adverse pathologic features and poor prognostic factors in different types of cancer, including nonsmall cell lung cancer, colorectal cancer, gastric cancer, and childhood acute lymphoblastic leukemia." (PMID 22988515, 2012). "Single-cell analyses localized TIMP1 to myeloid cells in colorectal cancer and fibroblasts in gastric cancer, linking it to apoptosis, EMT, angiogenesis, and stromal-immune crosstalk." (PMID 41613136, 2026). "We next evaluated the in vivo consequences of TIMP1 overexpression and cilengitide treatment using a colorectal cancer liver metastasis model." (PMID 41511313, 2025). "In this study, we identified tissue inhibitor of metalloproteinases-1 (TIMP1) as a key mediator in colorectal cancer (CRC) liver metastasis (CRLM), acting through a macrophage-dependent mechanism." (PMID 41511313, 2025). "Collectively, these results indicate that macrophages are the critical immune cell type responsible for transducing TIMP1’s pro-metastatic effects in colorectal cancer." (PMID 41511313, 2025). "Through multifactorial COX regression analysis, we identified TIMP1 as a crucial ferroptosis prognosis gene in colorectal cancer." (PMID 40687427, 2025). "To validate these findings in an independent model, we used MC38 colorectal cancer cells and TIMP1-conditioned medium (TIMP1-CM) to mimic TIMP1-rich tumor environments." (PMID 41511313, 2025). "We observed increased levels of numerous pro‐angiogenic proteins, including VEGF, PXDN, ANGPTL4 and TIMP‐1, a factor upregulated in colorectal cancer EVs that induces ECM remodelling in recipient fibroblasts." (PMID 41179923, 2025). "TIMP1 immunohistochemistry and TIMP1 serum concentrations were analyzed in a cohort of 776 colorectal cancer patients." (PMID 39789100, 2025).
colorectal cancer (continued). "Specifically in colorectal cancer, TIMP-1 plays a critical role in liver PMN formation through stromal-derived factor-1 (CXCL12)/CXCR4-dependent neutrophil recruitment." (PMID 41463352, 2025). "In contrast, tissue inhibitor of metalloproteinases (TIMP)-1 is critical for liver metastasis in colorectal cancer models." (PMID 41463352, 2025). "Previous research indicates that elevated TIMP1 expression significantly diminishes colorectal cancer patients’ overall survival rate, suggesting a poor prognosis." (PMID 40595862, 2025). "TIMP1 mRNA, identified through RNA sequencing, is significantly elevated in platelets from colorectal cancer patients compared to healthy controls and patients with inflammatory bowel disease." (PMID 40227568, 2025). "Several clinical studies have reported elevated serum levels of TIMP-1 in patients of colorectal cancer and lung cancer, suggesting TIMP-1 as a useful serum biomarker for the diagnosis and prognosis of cancers and inflammatory disorders." (PMID 41033464, 2025). "Our results also further supplement the importance of TIMP1 in predicting the occurrence and development of colorectal cancer." (PMID 40687427, 2025). "We found that high serum TIMP1 values independently predict worse overall survival of colorectal cancer patients, thus reinforcing the utility of serum TIMP1 as a prognostic marker." (PMID 39789100, 2025). "We observed increased levels of numerous pro-angiogenic proteins including TIMP-1, a factor upregulated in colorectal cancer EVs that induces ECM remodelling in recipient fibroblasts." (PMID 40654904, 2025). "In colorectal cancer, TIMP1 was shown to promote disease progression by modulating ferroptosis, immune infiltration, and redox-related metabolism." (PMID 41170378, 2025). "TIMP1 mRNA promotes tumor growth by transferring into colorectal cancer cells, highlighting its potential as an independent diagnostic biomarker and its role in tumor progression." (PMID 40227568, 2025). "Taken together, these results highlight that TIMP1 promotes macrophage M2 polarization and colorectal cancer liver metastasis via integrin-mediated signaling, and that cilengitide represents a promising therapeutic strategy to disrupt this axis." (PMID 41511313, 2025). "High expression of CXCL8 in colorectal cancer is part of the Myc/CXCL8/tissue inhibitor of metalloproteinase 1 (TIMP1) oncogenic mark." (PMID 40076892, 2025). "In particular, genes CDKN2A and TIMP1 have been shown to be closely related to the prognosis of colorectal cancer." (PMID 39120548, 2024). "TIMP1 is a prognostic marker of the progression and metastatic spread of colorectal cancer via the FAK-PI3K/AKT and MAPK pathways." (PMID 39769169, 2024). "Our study employed rigorous and systematic screening methods to enhance the credibility of TIMP1’s critical role in colorectal cancer diagnosis and prognosis." (PMID 37842645, 2023). "We have also shown that in colorectal cancer cells, exogenously added TIMP‐1 inhibits c‐Kit shedding and activates the c‐Kit signaling axis." (PMID 37081824, 2023). "Our rigorous inquiry revealed a compelling discovery: colorectal cancer cell lines with elevated TIMP1 expression exhibited significantly increased responsiveness to a selection of ten distinct pharmacological agents (log2FC < −1)." (PMID 37842645, 2023). "ROC curve analysis revealed that TIMP1 exhibited greater precision in distinguishing colorectal cancer tumor tissues from adjacent normal tissues." (PMID 37842645, 2023). "Through an exploration of the DepMap database, we conducted a comprehensive investigation into the pharmacological sensitivity of colorectal cancer cell lines, stratified based on the varying expression levels of the TIMP1 gene." (PMID 37842645, 2023). "In summary, the innovation of our study lies in the rigorous application of bioinformatics analysis methods, which enabled the identification of the TIMP1 gene with the greatest potential within colorectal cancer tissues." (PMID 37842645, 2023).
colorectal cancer (continued). "Previous studies suggest that TIMP1 is a critical mediator of inflammation and M2 macrophage polarization in colorectal cancer." (PMID 37108548, 2023). "Serum TIMP-1 plays a potential role in the diagnosis and prognosis of human cancers, including gastric and colorectal cancers." (PMID 35765478, 2022). "Transportation of the TIMP1 RNAs to colorectal cancer cells by platelets promote development of colorectal cancer." (PMID 34907282, 2021). "Recent studies have demonstrated that TIMP1 and TGA2B mRNA in tumor‐educated platelets are good diagnostic biomarkers for colorectal cancer and lung cancer, respectively." (PMID 33955587, 2021). "TIMP1 mRNA expressed in the platelets of colorectal cancer patients can be transported into colorectal cancer cells, thereby promoting tumor growth." (PMID 33619234, 2021). "With respect to the relation between TIMP1 and chemotherapy, high TIMP1 expression correlated with a positive response to 5-fluorouracil-based regimens in patients with colorectal cancer." (PMID 32774771, 2020). "In colorectal cancer, tissue inhibitor of metalloproteinases-1 (TIMP-1) promotes liver metastasis by triggering the formation of a pre-metastatic niche." (PMID 33101283, 2020). "We identified a proto‐oncogene, c‐Kit, as a potential mediator of metallopeptidase inhibitor 1 (TIMP‐1) function in colorectal cancer (CRC) cells." (PMID 31545548, 2019). "We found that TIMP1 mRNA levels are higher in platelets from colorectal cancer patients than in platelets from healthy volunteers and patients with inflammatory bowel diseases." (PMID 31639773, 2019). "Our aim is to investigate the prognostic role of MMP-8, − 9, and TIMP-1 in colorectal cancer (CRC) and their relationship to inflammation." (PMID 29929486, 2018). "In a study with 148 colorectal cancer patients, high serum MMP-8 and TIMP-1 associated with advanced stage." (PMID 29929486, 2018). "Some have shown that in colorectal cancer, preoperative plasma TIMP-1 serves as an independent prognostic marker, whereas others found only a limited value for TIMP-1 as a prognostic indicator." (PMID 29929486, 2018). "All in all, MMP-8 and TIMP-1 seem to influence the prognosis of colorectal cancer patients to a greater extent than MMP-9 seems to do." (PMID 29929486, 2018). "According to a meta-analysis based on five different studies, colorectal cancer patients with elevated plasma or serum TIMP-1 had poorer overall survival." (PMID 29929486, 2018). "The aim of our study was to investigate the prognostic roles of MMP-8, MMP-9, and TIMP-1 in colorectal cancer." (PMID 29929486, 2018). "Of median MMP-8, MMP-9, and TIMP-1 serum levels prior to surgery for colorectal cancer and for controls with benign disease, only TIMP-1 levels were higher in patients with CRC than in controls (P = 0.037, Mann-Whitney U-test)." (PMID 29929486, 2018). "The median level in the colorectal cancer patients increased from 98.5 ng/ml in stage I to 137.3 ng/ml in stage IV, with a significantly higher median TIMP-1 level found in stage IV patients compared to stage I–III." (PMID 27619981, 2016). "In a recent study, 4509 individuals, examined for colorectal cancer, had a median TIMP-1 level of 88.4 ng/ml (range 27.4–1166.0 ng/ml)." (PMID 27619981, 2016). "A study also showed that elevated TIMP-1 in colorectal cancer correlates with lymph node and distant metastases." (PMID 24143225, 2013). "Transcriptional analysis in colorectal cancer revealed that the expression of TIMP-1 in fibroblasts is even higher than that in tumor cells." (PMID 21745383, 2011). "The increased CXCL12 could be linked to increased tissue inhibitor of metalloproteinases (TIMP)-1 levels, and TIMP-1 levels in plasma correlate with liver metastasis in human colorectal cancer." (PMID 39653768, 2025). "Additionally, two genes, CDKN2A and TIMP1, stand out for their extensive study in colorectal cancer." (PMID 39120548, 2024).